ACACA (acetyl-CoA carboxylase alpha)
Diseases named in the same sentence as ACACA in open-access papers (continued):
Sharing a sentence is not in itself a finding about the gene and the disease.
cancer (continued). "Compared with normal tissues, the expression of FRGs with higher amplification frequency increased significantly in cancer tissues (e.g., SQLE, NFS1, and ACACA), and vice versa (e.g., GOT1, HMGCR, and FTH1)." (PMID 35444656, 2022). "ACACA (acetyl-CoA carboxylase or ACC1) is a key catalyzer in the biogenesis of long-chain fatty acids, which are essential for cancer cell survival during hypoxia." (PMID 35158968, 2022). "HPLC-MS/MS analysis showed that FASN, ACACA, α-tubulin, and β-tubulin were the target molecules, which SFN initiated anti-cancer signaling to downregulate." (PMID 34620841, 2021). "FASN uses substrates produced by the consequent activities of ACACA and ACLY enzymes, which, together with FASN have also been found to be deregulated in a number of cancer types." (PMID 34206240, 2021). "ACACA (acetyl‐CoA carboxylase or ACC1) catalyses the rate‐limiting reaction in the biogenesis of long‐chain fatty acids and is thus vital for cancer cell survival during hypoxia." (PMID 30809968, 2019). "In addition, we identified three heterozygous candidate missense variants in known cancer susceptibility genes (BMPR1A,BRIP1, and SRC), three truncating variants in possibly novel cancer genes (CLSPN,SEC24B, SSH2) and four candidate missense variants in ACACA, NR2C2, INPP4A, and DIDO1." (PMID 30809968, 2019). "Thus, ACACA and some fatty acids might play important roles in cancer cell survival." (PMID 31920968, 2019). "It would be important to test ACACA inhibitors in other IDH1 mutant cancers and design combination therapies for IDH1 mutant cancers using ACACA inhibitors and mutant-IDH1 inhibitors (such as AG-120)." (PMID 28561042, 2017). "We treated cancer cells with gradient concentrations of acetate and found that FASN and ACACA mRNA expression were upregulated in a dose-dependent manner under hypoxia." (PMID 27357947, 2016). "Therefore, we strongly recommend that the potential adverse effects of targeting ACACA or its derived therapeutic agents must be given extreme attention, especially in MAPK‐related cancers." (PMID 40066226, 2025). "Pan-cancer analysis across 33 distinct tumor types, employing ESTIMATE algorithm-derived metrics, revealed a consistently negative association between ACACA expression and TME characteristics." (PMID 41169354, 2025). "Dysregulation of critical genes (such as ACACA, FASN, and CPT1A) in fatty acid metabolism, leading to an imbalance in fatty acid degradation and production, was considered as a potential metabolic marker for cancer cells." (PMID 35076025, 2022). "Cancer cells develop capable de novo FAS machinery with an increase in the activity of key lipogenic enzymes such as adenosine triphosphate (ATP)-citrate lyase (ACLY), acetyl-CoA carboxylase (ACC), CoA carboxylase (ACACA), fatty acid synthase (FASN), and SCD." (PMID 33364199, 2020). "In the fatty acid synthetase part, ACACA and FASN were upregulated in 4 cancer types." (PMID 31828117, 2019). "Cancer cells prefer to derive their need for fatty acid via de novo lipogenesis in comparison to normal human tissues which prefers to utilize exogenous lipids, as a consequence of which cancer cells harbor high levels of FASN and ACACA." (PMID 26632252, 2015). "Furthermore, the overexpression of genes involved in fatty acid synthesis, such as the fatty acid synthase (FASN), acetyl-CoA carboxylase alpha (ACACA) and, the ATP citrate lyase (ACLY) can induce the development and progression of cancer." (PMID 24958265, 2013). "Furthermore, lipogenic enzymes that function upstream of FASN such as acetyl-CoA carboxylase-a (ACACA) and ATP citrate lyase (ACL) are also elevated in various cancers." (PMID 22266777, 2012). "Strikingly, ACACA expression exhibited significant negative correlations with the immune checkpoint-related genes (PDCD1, LAG3, LAGLS9, IDO1, CD244, CTLA4 and TIGIT), while showing positive associations with other genes (TGFBR1, KDR, IL10RB, CD160 and CD274) across most cancer types." (PMID 41169354, 2025).
cancer (continued). "Moreover, C75 treatment abrogated acetate-induced cancer cell survival without affecting FASN and ACACA mRNA levels." (PMID 27357947, 2016). "Interestingly, our results showed that the metastatic ability of ACACA-overexpression PBC cells did not change in a tail vein implantation model, compared with the PBC cells without doxycycline induction, suggesting that ACACA overexpression did not influence the spreading capacity of cancer cells." (PMID 36607556, 2023).
tumor (60 papers, 2012 to 2026). "Specifically, ACACA upregulation was positively linked to the activation of pathways related to fatty acid synthesis, tumor proliferation, TGF-β signaling, and the PI3K-AKT-mTOR pathway." (PMID 41169354, 2025). "A lncRNA derived from the MIR17HG, lnc-17–92, has been found to accelerate tumor growth by upregulating ACACA (an ACC1 encoding gene)." (PMID 38916672, 2024). "Of the HCC cases that had associated clinical data, ACACA expression positively associated with tumour grade." (PMID 28290443, 2017). "ACACA is one of very few purported SL partners of recurrent tumour mutations to have been validated in vivo." (PMID 28561042, 2017). "Single-cell analysis revealed that FASN and ACACA were predominantly expressed in tumor cells, while SPP1 was enriched in macrophages/monocytes." (PMID 42198359, 2026). "Then, single-cell RNA sequencing acquired from the Gene Expression Omnibus (GEO) database was employed to map the expression pattern of ACACA in the tumor microenvironment (TME)." (PMID 41169354, 2025). "ACACA expression was predominantly localized to epithelial cells, with comparable expression levels across tumor and normal tissues." (PMID 41169354, 2025). "To assess the effect of ACACA depletion on tumor metastasis in vivo, we used luciferase‐coupled shRNA to knock down the ACACA in DU145 cells." (PMID 40066226, 2025). "First, we conducted a comprehensive analysis to investigate the correlations of ACACA expression levels with key clinical outcomes, we also examined its involvement in immune cell infiltration and the tumor-immune landscape." (PMID 41169354, 2025). "As a key metabolic regulatory enzyme, ACACA’s oncogenic activity is affected by the metabolic heterogeneity of tumor cell subpopulations, and depends on hypoxia and nutrient conditions in the microenvironment." (PMID 41169354, 2025). "Subsequent functional experiments showed that targeted knockdown of ACACA can reduce the proliferation, metastasis, and lipid synthesis capabilities of tumor cells." (PMID 41169354, 2025). "In LUAD, ACACA mRNA expression was significantly elevated in the M1-stage tumors, indicating its potential involvement in tumor metastasis." (PMID 41169354, 2025). "Subsequent CellChat analysis revealed enhanced interactions between ACACA-high tumor cells and CD8+ T cells, primarily via secreted signaling pathways like the macrophage migration inhibitory factor (MIF) axis (MIF-CD74+CXCR4, MIF-(CD274+CD44))." (PMID 41169354, 2025). "The elevated expression of ACACA was relevant to worse tumor stages, grades, metastases and poor survival in many types of human tumors, especially in LIHC." (PMID 38584256, 2024). "SMS can influence the metabolic process and is involved in tumor growth.Overexpression of ACACA, ME1, ADSL or S100A10 promotes HCC growth, migration or invasion, and is connected with poor prognosis." (PMID 36632140, 2023). "Citrus-limon juice-derived ELNs inhibit tumor cell growth through a significant downregulation of the Acetyl-CoA Carboxylase 1 (ACACA)." (PMID 35757759, 2022). "The DU145-sh-NC and DU145-sh-ACACA-c cell lines were used to detect the effect of ACACA on the tumor growth in nude mice so as to test the in vivo biological function of ACACA." (PMID 33391420, 2021). "ACACA is the first important step in catalysing the synthesis of fatty acids in the cytoplasm of mammals and is a key gene that regulates tumour cell survival." (PMID 34418989, 2021). "The tumor volume was smaller in the DU145-sh-ACACA-c group than in the DU145-sh-NC group after 30, 42, 45, and 48 days (P < 0.05)." (PMID 33391420, 2021). "In terms of lipid metabolism, ACACA impacts the rate-limiting step in fatty acid synthesis and is a key regulator of tumor cell survival." (PMID 32760210, 2020).
tumor (continued). "Expression of ACACA, the rate‐limiting enzyme of fatty acid biosynthesis, in a PCa tissue microarray has been reported to be significantly higher than in non‐malignant tissue and inhibition of this enzyme inhibits tumor growth and increases apoptosis in PCa." (PMID 40066226, 2025). "Additionally, comprehensive multi-algorithmic analysis (TIMER 2.0, xCell, MCPCOUNTER, EPIC, CIBERSORT) revealed a dual role of ACACA in shaping the tumor immune landscape across malignancies." (PMID 41169354, 2025). "Inhibiting ACACA effectively suppressed fatty acid synthesis and tumor growth." (PMID 41169354, 2025). "The transportation of acetate into the cell via MCT1, followed by its translocation into the nucleus, resulted in the activation of oncogenes by enhancing the acetylation of histone H3K27 in the promoter region of the FASN and ACACA genes, ultimately promoting tumor progression." (PMID 40612939, 2025). "We further demonstrated that ACACA was closely related with tumor immune microenvironment and could serve as a immunotherapeutic biomarker." (PMID 41169354, 2025). "The expression of CYP7A1, ELOVL1 and ACACA were higher in LIHC tumor tissues than normal tissues." (PMID 38584256, 2024). "The mutation frequencies of FAM83B, ZNF585A, DMBT1, ACACA, NOVA1, PCTH1, and ADAMTS7 were significantly higher in the high‐risk group, suggesting that these mutations may contribute to tumor development." (PMID 35616307, 2023). "The results demonstrated that inhibition of ACACA could suppress fatty acid synthesis and tumor growth." (PMID 38049827, 2023). "Acetyl-coenzyme A carboxylase α (ACACA) was strongly positive in most normal renal tissues after staining with the HPA063018 antibody (highly positive in renal tubular cells) but moderately positive in most tumor tissues." (PMID 37056387, 2023). "Thus, superenhancer‐associated FASRL expression driven by USF1 promoted tumor progression through the interaction between FASRL and ACACA to increase FA synthesis." (PMID 36307901, 2022). "ACACA mainly acts on the first stage of fatty acid synthesis, and is one of the rate-limiting enzymes that regulate fat and metabolism, and plays a vital role in the tumor cells survival." (PMID 35354376, 2022). "At the same time, ACACA also promoted the synthesis of some genetic material (related to long-chain fatty acid beta-oxidation or cell membrane formation), ultimately promoting the growth of tumor cells." (PMID 33391420, 2021). "Indeed, tumor cells often overexpress acetyl-CoA carboxylase (ACACA), ATP citrate lyase (ACLY), and fatty acid synthase (FASN), key enzymes responsible for de novo biosynthesis of fatty acids, which makes them attractive targets for therapeutic interventions." (PMID 34206240, 2021). "The effect of ACACA on tumor formation in vivo was analyzed." (PMID 33391420, 2021). "In addition, down-regulation of ACACA gene inhibited tumor formation in a nude mouse model." (PMID 33391420, 2021). "To characterize the role of ACACA in the LUAD TME, we integrated single-cell transcriptomic datasets from normal lung (nLung), early-stage (tLung), and advanced tumor (tL/B) tissues derived from the GSE131907 dataset." (PMID 41169354, 2025). "Further bioinformatics analysis of miR-24-1-5p targets, including CD34, ACACA, TPM3, UFC1, EDIL3, and CHEK1, reinforces their role in tumor immune cell infiltration and the transformation of the tumor microenvironment." (PMID 38840234, 2024). "The regulation of de novo lipogenesis affects the tumor’s energy supply and is divided into two phenotypes: ACC1 (ACCα or ACACA) and ACC2 (ACCβ or ACACB)." (PMID 38189049, 2023). "Using bioinformatics, we screened six genes for their potential to influence tumor lipid metabolism (ADH1C, APEX1, ME1, S100A10, ACACA, and CYP2C9), and a prognosis model for HCC patients was constructed." (PMID 36456877, 2022). "In fact, mRNA levels of enzymes of FA synthesis pathway was significantly increased in tumor cells, including ACLY, ACACA, and FASN." (PMID 34206240, 2021).
tumor (continued). "Inhibition of fatty acid synthesis in vivo, both targeting ACACA with TOFA or FASN with either Orlistat or UB006, not only reduced tumor growth, but importantly led to neural differentiation, as assessed by expression of differentiation markers." (PMID 33659885, 2021). "The ACACA, AR, MAPK, PDK1, PEA15, and SYK showed significant differential expression between normal tissues and tumor tissues (P < 0.0001)." (PMID 33842538, 2021). "In summary, three genes (ACACA, SQLE, and PHKG2) in the newly developed signature have established roles in the protection of tumor cells against ferroptosis, whereas TFRC has the opposite effect." (PMID 33989111, 2021). "Mir-195 has been shown to target Bcl-2, inducing apoptosis, and target FASN, HMGCR, ACACA and CYP27B1 in hormone-receptor positive breast cancer cell lines, suppressing tumour growth, EMT, invasion and metastasis." (PMID 31077182, 2019). "For instance, the treatment of EC cells with inhibitors of ACACA, ELOVL1, or FASN would directly test the hypothesis that increased de novo lipogenesis promotes tumor growth." (PMID 40244177, 2025). "Finally, we evaluated the expression of ACACA and FASN in tumour tissues obtained from xenograft experiments using human TNBC cells using immunohistochemistry." (PMID 37268670, 2023). "Consistently, the higher expression level of indispensable genes for DNL, including ATP citrate lyase (ACLY), acetyl-CoA carboxylase alpha (ACACA), and fatty acid synthase (FASN) were observed in tumor tissue, further corroborating the pronounced DNL during hepatocarcinogenesis." (PMID 35406630, 2022). "In addition, in mice with tumor formation in situ, the tumor bodies of the group with high expression of PPARG also had higher expression levels of genes related to fatty acid metabolism, such as ACACA, ACLY and ACSS2 and so on." (PMID 40303293, 2025). "The differential expression of ATP citrate lyase (ACLY), acetyl-CoA carboxylase alpha (ACACA), fatty acid synthase (FASN), SCD, and SREBF1 was further validated via RT‒qPCR subsequent to magnetic-based cell sorting of co-cultured H2228 and H3122 tumor spheroids." (PMID 40524253, 2025). "The mRNA expression of ACACA and SCD1 was not different between the tumor and non-tumor tissue." (PMID 40076869, 2025).
metabolic disease (10 papers, 2014 to 2024). A congenital disorder (due to inherited enzyme abnormality) or acquired (due to failure of a metabolically important organ) disorder resulting from an abnormal metabolic process. "ACACA, a key regulator and an essential rate-limiting enzyme of fatty acid synthesis and oxidation process, is regarded as an attractive target for FAs metabolic diseases." (PMID 38584256, 2024). "For example, targeting ACACA has the advantage that, since this enzyme has long been considered a target in the treatment of metabolic diseases, there are a number of inhibitors already available." (PMID 28412757, 2017). "Although AMPK has a directly regulatory effect on ACACA with many metabolic diseases, its specific mechanism in the progression of NAFLD remains unclear." (PMID 38395901, 2024). "ACACA may induce dysregulation of lipid metabolism in human and mouse is known to result in metabolic diseases, such as obesity and diabetes, it may also result in severe metabolic disorders in lactating cows." (PMID 34868267, 2021).
infectious disease (2 papers, 2017 to 2020). A disorder directly resulting from the presence and activity of a microbial, viral, or parasitic agent in humans. "In addition, lipid synthesis inhibition is a strategy to fight microbial infections that are known to take advantage of cell lipid storage, and ACACA inhibitors have been designed to develop antimicrobial strategies in infectious diseases." (PMID 32781626, 2020).
adenocarcinoma (1 paper, 2018). A common cancer characterized by the presence of malignant glandular cells. "INS, TOP2A, ACACA, ALB, and TXN are the key genes which play an important role in adenocarcinoma." (PMID 30425814, 2018).
blood cancer (1 paper, 2021). "Within hematological cancer cell lines, the coessentiality network is significantly restructured, with the ACACA/FASN module correlated with SCD in most backgrounds (r = 0.35, P < 10−18) but strongly anticorrelated in 36 blood cancer cell lines (r = −0.52, P < 10−3)." (PMID 34764293, 2021).
hematological malignancies (1 paper, 2011). "ACACA, RARA, NOTCH1 and NUP214 are known to form translocations in various types of hematological malignancies while many other fusion genes involve suspected oncogenes, such as RPS6KB1 (RPS6KB1-TMEM49 and RPS6KB1-SNF8), GSDMB (TATDN1-GSDMB) and MCF2L (LAMP1-MCF2L)." (PMID 21247443, 2011).
infection (1 paper, 2024). The state of being infected such as from the introduction of a foreign agent such as serum, vaccine, antigenic substance or organism. "EBV early infection also boosts key fatty acid synthesis enzymes, ACACA and FASN, to convert acetyl-CoA derived from glycolysis into palmitate, facilitating lipogenesis." (PMID 38659762, 2024).
neurodevelopmental disorder (1 paper, 2020). A behavioral and cognitive disorder with onset during the developmental period that involves impaired or aberrant development of intellectual, motor, or social functions. "This suggested that there might be other protein-coding genes at 17q12 that contributed for the neurodevelopmental disorder, such as LHX1 and ACACA, and were referred to as the genes involved in the neurodevelopmental syndrome." (PMID 32429945, 2020).
ACACA also shares sentences with these, for which no sentence is quoted: glioblastoma (4 papers); acute myeloid leukemia (2); allergic asthma (2); colorectal cancer (2); esophageal cancer (2); non-alcoholic fatty liver disease (2); viral infection (2); Abdominal obesity (1); adenoma (1); Anxiety (1); autoimmune disease (1); Autoimmunity (1); bacterial infections (1); benign tumors (1); breast (1); breast invasive carcinoma (1); breast tumor (1); B‐cell lymphoma (1); cervical squamous cell carcinoma (1); colitis (1); colon adenocarcinoma (1); Cushing syndrome (1); endocrine disease (1); endometriosis (1); experimental autoimmune encephalomyelitis (1); head and neck squamous cell carcinoma (1); hematological cancer (1); Hepatic fibrosis (1); Hyperinsulinemia (1); hypertriglyceridemia (1).
A further 21 diseases each share a sentence with ACACA in 1 paper.